CD160 (CD160 molecule)
Diseases named in the same sentence as CD160 in open-access papers (continued):
Sharing a sentence is not in itself a finding about the gene and the disease.
malaria (3 papers, 2018 to 2024). Malaria is a serious and sometimes fatal disease caused by a parasite that commonly infects a certain type of mosquito which feeds on humans. "In conclusion, CD160 is specifically expressed on highly activated CD8+ T effector cells that are harmful during the blood-stage of malaria." (PMID 30483269, 2018). "Notably, in line with our studies, two recent studies reported that CD160+ CD8+ T cells play positive roles in immune responses against malaria and listeria." (PMID 33072082, 2020). "Importantly, our data during malaria now strongly support the idea of CD160 as a critical regulator of CD8+ T cytotoxicity and consequent detrimental function on the overall outcome of malaria." (PMID 30483269, 2018). "Subsequently, we analyzed the expression of the cytotoxic molecule GzmB and Perforin the proliferation marker Ki67 and the co-inhibitory receptor PD-1, both in CD8+CD160+ and CD8+CD160− T cells from healthy controls or malaria patients." (PMID 30483269, 2018). "Taken together, these data identify CD160 as signature of CD8+ T cell with high killing capacity and IFNγ production in the context of blood-stage malaria." (PMID 30483269, 2018). "Furthermore, we examined the induction of CD160 on CD8+ T cells in a non-lethal model of malaria via injection of the parasite Plasmodium yoelii (PyNL)." (PMID 30483269, 2018).
Acute hepatitis (2 papers, 2019 to 2021). Acute hepatic injury resulting from inflammation typically accompanied by increased serum alanine transaminase activity. "We next investigated whether CD160 contributes to NKT cell activation in more physiologic settings of acute hepatitis." (PMID 31332204, 2019). "Although its ligand HVEM functions as a bidirectional switch in T cells, whereby the outcome depends on the receptors engaged, the functional consequence of CD160/BTLA/HVEM interactions in NKT cells is co-inhibitory, with deficiency aggravating NKT-mediated acute hepatitis." (PMID 31332204, 2019). "Furthermore, both BTLA and CD160 are expressed by iNKT cells, and both molecules served to attenuate production of inflammatory cytokines by iNKT cells during αGalCer-induced acute hepatitis, providing an example in which two HVEM-binding IgSF molecules are required in one cell type." (PMID 34709351, 2021). "Interestingly, CD160−/− NKT cells downregulated surface BTLA during acute hepatitis." (PMID 31332204, 2019). "Here, we present data showing that the CD160/HVEM signaling axis delivers a BTLA-independent negative signal to NKT cells in both α-GalCer and Con A-induced acute hepatitis." (PMID 31332204, 2019).
Hepatitis (2 papers, 2019 to 2021). Inflammation of the liver. "In both α-GalCer- and Con A-induced murine hepatitis models, CD160−/− mice suffered from severe inflammation with elevated IL-4, IL-6, IFN-γ, and TNF-α and could not fully recover from lethal Con A challenge." (PMID 31332204, 2019). "Therefore, aberrant activation of NKT cells, but not surrounding APCs, was primarily responsible for acute inflammation during α-GalCer-induced hepatitis in the absence of CD160." (PMID 31332204, 2019). "To assess whether the activation status of DCs was altered in the absence of CD160, we measured the levels of multiple ligands on DCs, including CD1d, CD40, CD80, CD95, PD-L1, and HVEM, during α-GalCer-induced hepatitis." (PMID 31332204, 2019).
influenza (2 papers, 2014 to 2016). An acute viral infection of the respiratory tract, occurring in isolated cases, in epidemics, or in pandemics; it is caused by serologically different strains of viruses (influenzaviruses) designated A, B, and C, has a 3-day incubation period, and usually lasts for 3 to 10 days. "Co-targeting of PD-1 with either CD160 or HVEM showed very low levels of enhancement when peptide pools specific to other infectious agents (CEFT: CMV, EBV, Influenza and Tetanus) were used as controls." (PMID 25179432, 2014).
Acute hepatic failure (1 paper, 2019). Hepatic failure refers to the inability of the liver to perform its normal synthetic and metabolic functions, which can result in coagulopathy and alteration in the mental status of a previously healthy individual. "In this context, accelerated NKT cell activation in CD160−/− mice could be due to increased availability of HVEM on CD4+ T cells, which could, in turn, lead to severe inflammation and acute hepatic failure." (PMID 31332204, 2019).
acute myeloid leukemia (1 paper, 2025). Acute myeloid leukemia (AML) is a group of neoplasms arising from precursor cells committed to the myeloid cell-line differentiation. "Their NK cells downregulate the expression of CD160, and low expression of CD160 is associated with shorter survival of patients with acute myeloid leukemia." (PMID 40062730, 2025).
autoimmune hepatitis (1 paper, 2019). Hepatitis caused by autoantibodies. "To define the role of CD160 on NKT cells in an autoimmune hepatitis model, we first measured surface CD160 expression on NKT cells after Con A (15 mg/kg) administration in vivo." (PMID 31332204, 2019). "To further investigate the role of CD160 receptor in an autoimmune hepatitis model, we injected a lethal dose (30 mg/kg) of Con A i.v. into WT and CD160−/− mice with and followed their survival over time." (PMID 31332204, 2019).
breast tumor (1 paper, 2022). "Here we found significantly lower methylation of CD160, ISYNA1 and RAD51B were correlated with hormone receptor status, increased breast tumor size, advanced tumor stage and more lymph node involvement." (PMID 35812748, 2022).
brucellosis (1 paper, 2024). Brucellosis is a bacterial infection that spreads from animals to people via unpasteurized dairy products or by exposure to contaminated animal products or infected animals. "Further analysis found that Th1 cells had the highest exhaustion scores in brucellosis patients, and highly expressed multiple inhibitory receptors (e.g., LAG3, CD160, CTLA4)." (PMID 39135683, 2024).
cerebral malaria (1 paper, 2018). A sequestration of Plasmodium falciparum in the brain, which can cause coma and/or seizures. "In this study we addressed this unanswered question by generating CD160-deficient mice and analyzing the CD8+ T cell profile during experimental cerebral malaria." (PMID 30483269, 2018). "Hence, we further correlated CD160 expression on CD8+ T cells with the development of cerebral malaria." (PMID 30483269, 2018).
cholangiocarcinoma (1 paper, 2021). A carcinoma that arises from the intrahepatic biliary tree (intrahepatic cholangiocarcinoma) or from the junction, or adjacent to the junction, of the right and left hepatic ducts (hilar cholangiocarcinoma). "In the present study, PANX1 was shown to have a negative correlation with CD160 in various tumors, such as LGG (rho = −0.480, P < 2.2e-16), KIRP (rho = −0.371, P = 9e-11) and cholangiocarcinoma (CHOL) (rho = −0.41, P = 0.0137)." (PMID 34796785, 2021).
chronic hepatitis B (1 paper, 2021). "Decreased CD160 expression has been reported in peripheral NK cells from chronic hepatitis B patients and in intratumor NK cells from HCC patients." (PMID 34198593, 2021).
chronic hepatitis C (1 paper, 2017). "CD160 is another inhibitory molecule linked with T cell exhaustion, and overexpression of CD160 was observed on HCV-specific CD8+ T cells from patients with chronic hepatitis C." (PMID 28703774, 2017).
cutaneous leishmaniasis (1 paper, 2018). Leishmaniasis affecting the skin. "Consequently, the expression of PD-1, CTLA-4, 2B4, CD160, and TIM-3 was evaluated ex vivo in PBMCs from 10 HD, 4 asymptomatic subjects, 5 patients cured of cutaneous leishmaniasis and 4 patients with active CL." (PMID 30510917, 2018).
depression (1 paper, 2024). "We observed an increase in CD3 + CD160 + CD244 + T cells in SLE patients with persistent proteinuria, high disease activity, and C3/C4 depression." (PMID 38650001, 2024).
Down syndrome (1 paper, 2022). "The levels of expression of the single receptor CD160+ and co-expression of all three inhibitory receptors, CD4+PD-1+CD160+CD244+ T cells, were similar for children with Down syndrome and healthy controls." (PMID 35222360, 2022).
endometriosis (1 paper, 2022). The growth of functional endometrial tissue in anatomic sites outside the uterine body. "The expression of CD160 was elevated in the women with endometriosis compared to the control group women." (PMID 36313261, 2022). "The high expression of CD160 is believed to be one of the factors that plays a role in decreasing CD4+ expression in women with endometriosis because the bond between CD160 and its ligand inhibits the activation of CD4+ T cells." (PMID 36313261, 2022). "However, the role of CD160-expressing T cells in women with endometriosis is poorly understood and should be investigated separately." (PMID 36313261, 2022). "The expression of CD160 was downregulated in the endometriosis group after stimulation." (PMID 36313261, 2022). "Increased expression of CD160 and decreased CD28 play a role in inhibiting NK cell activation and T cell response in women with endometriosis." (PMID 36313261, 2022). "In conclusion, this study, combined with a previous one, demonstrated that the increased expression of CD160 and decreased expression of CD28 may play a role in inhibiting NK cell activation and T cell response in endometriosis." (PMID 36313261, 2022). "In this study, it was also found that there was no change in CD160 expression after being treated with IL-2 in both the endometriosis and control groups." (PMID 36313261, 2022).
gastric tumor (1 paper, 2022). "The interaction between EP11-CLDN7 and CD8+ T cells was dominated by the interactions of LGALS9—HAVCR2 and HVEM—CD160 both of which are well-known checkpoints that inhibit CD8 + T cell functionality, suggesting an immunosuppressive function of the gastric tumor cells." (PMID 36550535, 2022).
gout (1 paper, 2022). A condition characterized by painful swelling of the joints, which is caused by deposition of urate crystals. "Three LD blocks existed in chromosome 1 for the variants relating to gout, which were composed of genes DNAJC16, AGMAT (first block), PDZK1, CD160, NUDT17 (second block), TRIM46, MUC1, MTX1, and ASH1L (third block)." (PMID 36221101, 2022).
liver cirrhosis (1 paper, 2021). "Thus, it is possible that the downregulation of CD160 on peripheral CD56dim NK cells might result from systemic immune exhaustion due to HCC-bearing liver cirrhosis." (PMID 34198593, 2021). "We found the decrease of CD160, Siglec-7, NKp46 and NKp30 expression and increase of CD49a, Siglec-10, PD-1 and ILT2 expression on peripheral NK cells in HCC patients with liver cirrhosis, compared with HVs." (PMID 34198593, 2021).
low grade glioma (1 paper, 2021). A grade I or grade II glioma arising from the central nervous system. "Overall, we observed significant association between IGSF10 and immune checkpoint genes such as CD200R1, VSIR, CD160, CD28, BTLA, and CD40LG in several tumors including low-grade glioma (LGG) and thyroid carcinoma (THCA)." (PMID 34351868, 2021).
macular degeneration (1 paper, 2022). Loss of vision in the central portion of the retina (macula), secondary to retinal degeneration. "We identified an eQTL associated with CD160 in RPE2 (rs10910829) which also had a significant interaction between disease and genotype; whilst this gene is associated with macular degeneration—it is primarily involved in neovascular disease." (PMID 35882847, 2022).
ocular infection (1 paper, 2020). "To further assess the contribution of HVEM binding partners in disease severity, we used a Luneau Cochet-Bonnet esthesiometer to measure the blink response in BTLA−/−, LIGHT−/−, and CD160−/− mice following HSV-1 ocular infection." (PMID 32398314, 2020).
Plasmodium falciparum malaria (1 paper, 2018). Malaria resulting from infection by Plasmodium falciparum. "Importantly, CD160 is also induced on cytotoxic CD8+ T cells during acute Plasmodium falciparum malaria in humans." (PMID 30483269, 2018).
renal carcinoma (1 paper, 2024). A carcinoma arising from the epithelium of the renal parenchyma or the renal pelvis. "Given the negative correlation of CD160 expression with clinical prognosis in ESCC and other tumours such as renal cancer, we postulate that CD160-expressing cancer cells could use the HVEM and BTLA inhibitory pathways to inhibit T and NK cells activities." (PMID 39419971, 2024).
rheumatoid arthritis (1 paper, 2021). A chronic, systemic autoimmune disorder characterized by inflammation in the synovial membranes and articular surfaces. "A study found that CD160 rs744877 was closely related to the susceptibility of rheumatoid arthritis (RA) and may be involved in the development of RA." (PMID 34238277, 2021).
sarcoma (1 paper, 2024). A usually aggressive malignant neoplasm of the soft tissue or bone. "T‐cells in the sarcoma microenvironment exhibited elevated levels of cytotoxicity (GZMB, GNLY and KLRD1), exhaustion (HAVCR2, CD38, CD160, CXCL13 and CX3CR1), and inflammation (IL33, PPARG, IL6R and SOCS3), suggesting an activated but exhausted phenotype." (PMID 39658531, 2024).
squamous carcinoma (1 paper, 2024). "Of note, XCL1 was predominantly expressed in cancer cells showing adenocarcinoma morphology and dysplastic cells in the submucosa glands, while CD160 could be expressed in both squamous carcinoma and adenocarcinoma cells as well as in the proliferative and dysplastic cells of the submucosa glands." (PMID 39419971, 2024).
testicular germ cell tumor (1 paper, 2022). A germ cell tumor arising from the testis. "Additionally, UPF3B expression was positively correlated with most immunoinhibitors, including TGFBR1, IL10RB, CD160, CD274, TIGIT and PDCD1 in UVM, OV, KIHC, and LIHC, but negatively associated with the expression of majority genes in STAD and Testicular Germ Cell Tumors (TGCT)." (PMID 36194583, 2022).
trigonocephaly (1 paper, 2017). "Likewise, none of the genes duplicated in patient 6 (NBPF20, GPR89A, PDZK1, CD160, RNF115) are known to cause trigonocephaly." (PMID 28724436, 2017).
tumor (82 papers, 2012 to 2026). "Defects in CD160 have been implicated as a potential cause of tumor immune escape, suggesting its therapeutic potential in inhibiting tumor metastasis." (PMID 40092490, 2025). "Polymorphisms in the HVEM and CD160 genes, along with gender, age at diagnosis disease stage, tumor size, and the presence of metastasis or necrosis, were incorporated into the overall survival (OS) analysis." (PMID 38999968, 2024). "CD160 preferentially binds to the herpes virus entry mediator (HVEM), and engagement of CD160 with this ligand activates NK-cell function, causing increased IFN-γ and TNF-α secretion, and in the tumor microenvironment, the activation of CD160 on immune cells promotes target cell cytolysis." (PMID 36110864, 2022). "We detected multiple NK cell family receptor encoding genes (e.g., KLRK1, NCR2, CD2, and CD160) which might be critical in mediating anti-tumour immune responses against BLCA because higher expression of these genes was associated with better patient survival probabilities." (PMID 39877370, 2024). "C2, characterized as a cold tumour with reduced immune cells and antigen presentation, exhibits high expression of immunoinhibitor CD160, suggesting targeting CD160 provides a novel immunotherapy strategy for patients of C2." (PMID 41292185, 2025). "HVEM and its inhibitory receptors BTLA and CD160 have become the focus of intensive tumor research as a potential new therapeutic target or prognostic marker." (PMID 40243455, 2025). "Research indicates that co-expression and association of CD96 and CD160 with CD318 influence the regulation and activation of CD8+ T cells and NK cells, thereby affecting cytotoxic responses and anti-tumor immunity." (PMID 40725832, 2025). "The expression levels of immune checkpoints, including BTLA, VTCN1, CD276, PDCD1, CD160, NRP2, and CD200, as well as the tumor-associated fibroblast marker FAP, were found to be higher in the high-risk group." (PMID 40364849, 2025). "CD160, which is highly expressed in natural killer cells, plays a significant role in killing tumor cells." (PMID 38807380, 2024). "Of note, several negative regulators of anti-tumor responses were down-regulated in CUL5 KO cells including exhaustion-associated biomarkers (NR4A2, PDCD1 and CD160), myeloid-derived suppressive cell promoting cytokine CSF2, and pro-apoptosis factor BCL2L11." (PMID 38242867, 2024). "By screening a panel of solid tumors to evaluate NK cell infiltration by immunochemistry, we unexpectedly observed a strong expression of CD160 in TNBC tumor biopsies." (PMID 38360636, 2024). "The obtention of a specific CD160-TM, able to promote targeted tumor cell depletion, opens new and attractive perspectives for the development of anti-CD160-TM therapeutic antibodies in the current field of TNBC treatments." (PMID 38360636, 2024). "A very special finding was that all kinds of receptors were least expressed in normal tissues, with the exception of CD160, which was expressed more in normal tissues than in tumor tissues (Kruskal-Wallis test, p < 0.001)." (PMID 39120585, 2024). "Our finding of tumour cells overexpressing NK cell markers XCL1/2 and CD160 correlating with the lowest level of immune cell infiltration suggests a tumour-intrinsic immune evasion mechanism of ESCC." (PMID 39419971, 2024). "To study the potential anti-tumor function of 22B12 mAb in vivo, we used a xenograft mouse model of CD160-TM+ TNBC tumor in the SCID mouse, known to retain partially functional NK cells and fully functional macrophages." (PMID 38360636, 2024). "Preliminary data obtained by IHC on TNBC patients' tumor biopsies revealed an unconventional expression of CD160 by TNBC tumor cells." (PMID 38360636, 2024).